FHIT (fragile histidine triad diadenosine triphosphatase)
Diseases named in the same sentence as FHIT in open-access papers (continued):
Sharing a sentence is not in itself a finding about the gene and the disease.
cancer (continued). "Whereas many studies have focused on the molecular roles of APOBEC3B, and to some extent APOBEC3A, possible cumulative effects of action of APOBEC3A, APOBEC3B, UNG, REV1, and FHIT on generation of APOBEC3B-like mutation motifs and on drug sensitivity in cancer have not been clearly elucidated." (PMID 29642934, 2018). "In addition, data mining of over 6,500 TCGA cancers identified FHIT as the gene exhibiting the most significant, and negative, correlation with mutational signature 5 (Spearman p= 2.00E-65, MM Regression p= 1.90E-25)." (PMID 29254236, 2017). "In validation stage, 950 Caucasian samples, including 126 paired samples from TCGA, 568 cancer tissues and 256 normal controls from GEO database were analyzed, and all 8 CpG sites near the promoter region of FHIT gene were not significantly differentially methylated." (PMID 28036263, 2017). "Thus it is possible that the FHIT locus is not very fragile in epithelial cells, from which most cancers with FHIT deletions derive." (PMID 23209436, 2012). "In both studies, the BBD lesions examined were adjacent to cancer tissues and the staining characteristics observed may not be a reflection of the true FHIT status as this could have arisen from a local field effect." (PMID 17164758, 2007). "However, a more global question, is whether FHIT methylation inclines any individual to a wide array of cancers, not just ATL?" (PMID 35663592, 2021). "Copy number losses of CRK (P = 0.07), SMAD2 (P = 0.09), FHIT (P = 0.68), and NFATC1 (P = 0.11) genes did not vary significantly between diffuse-type cancers and intestinal-type cancers." (PMID 26360582, 2015).
adenocarcinoma (8 papers, 2003 to 2022). A common cancer characterized by the presence of malignant glandular cells. "The high frequency of deletions found at the FHIT locus may indicate a possible role for this locus in male patients with adenocarcinomas." (PMID 15150628, 2004).
infection (6 papers, 2005 to 2023). The state of being infected such as from the introduction of a foreign agent such as serum, vaccine, antigenic substance or organism. "An association between FHIT gene abnormalities and infection with particular HPV types has been suggested, since 87% of the cases with absent FHIT expression were positive for HPV16 infection." (PMID 16004614, 2005). "We also tested A549 cell proliferation rate after Annexin 4 silencing or infection with Ad-FHIT at MOI25 or combined treatments." (PMID 24223161, 2013).
neurological disease (2 papers, 2021 to 2022). "Moreover, HTLV-I infected carriers, and those that presented with TSP/HAM, a neurological disease, rarely carried methylated FHIT." (PMID 35663592, 2021).
benign tumors (1 paper, 2008). "FHIT protein is an accessible target in molecular biology laboratory used to judge various benign tumors." (PMID 18366613, 2008). "The high expression level of tumor suppressor gene FHIT may suggest benign tumor." (PMID 18366613, 2008).
gastrointestinal tumours (1 paper, 2020). "Low expression of the FHIT gene plays an important role in the prognosis of gastrointestinal tumours." (PMID 32943986, 2020).
hematological malignancies (1 paper, 2024). "Studies have observed that dysregulation or loss of FHIT mRNA expression occurs frequently in various cancers but loss of the Fhit protein has been seen in various hematological malignancies as well." (PMID 38587694, 2024).
FHIT also shares sentences with these, for which no sentence is quoted: schizophrenia (4 papers); autism (3); liver cancer (3); thyroid cancer (3); Anxiety (2); carcinoma in situ (2); gastric adenocarcinoma (2); head and neck squamous cell carcinoma (2); Hypertension (2); kidney cancer (2); neuroblastoma (2); adult T-cell leukemia (1); alcoholism (1); anal carcinoma (1); anaplastic thyroid cancer (1); Anorexia (1); asthma (1); astrocytoma (1); autism spectrum disorder (1); benign breast disease (1); carcinomas of the larynx (1); chronic gastritis (1); Cirrhosis (1); colorectal (1); diabetes (1); differentiated thyroid carcinoma (1); diffuse large B-cell lymphoma (1); ductal carcinoma in situ (1); dysplasia (1); erythroplakia (1).
A further 34 diseases each share a sentence with FHIT in 1 paper.